TNF (tumor necrosis factor)
Diseases named in the same sentence as TNF in open-access papers (continued):
Sharing a sentence is not in itself a finding about the gene and the disease.
tumor (continued). "In our study, compared with the control cells, supernatant-treated RAW 264.7 macrophages released small quantities of NO, IL-6, and TNF-α and a large quantity of TGF-β, suggesting that the macrophages acquired tumor-promoting activities." (PMID 29155869, 2017). "The requirement for TNF by the CD8+ T cell response has previously been shown to differ depending on the inflammatory context, with T cell responses to weak tumor antigens showing greater TNF dependence than a strong anti-LCMV response." (PMID 28886201, 2017). "These cells produce cytokines, which are cytotoxic mediators like reactive oxygen species (ROS), tumor necrosis factor-alpha (TNF-α), and interleukins, leading to tumor progression." (PMID 27911876, 2017). "Tumor necrosis factor-α (TNF-α) is a central mediator of inflammation, tumor growth control, autoimmunity, and immune response to infection." (PMID 29184553, 2017). "Interestingly, elevation in serum TNFα and IL-6 were prevented in Rab27-deficient LLC tumor-bearing mice where serum Hsp70/90 and EV levels were not elevated, suggesting that elevated serum Hsp70 and Hsp90 mediate the systemic increase of inflammatory cytokines in tumor hosts." (PMID 28928431, 2017). "The cytokines in the tumor microenvironment can either promote antitumor immunity (IL-12, IFN-γ), enhance tumor development and progression (IL-6, IL-17, IL-23), or influence the cancer cell growth and survival (TRAIL, FasL, TNF-α, TGF-β, IL-6)." (PMID 28101811, 2017). "Serum CCL2, IL-10, IL-5, IL-4, TNF-α, IL1-β and IL-12p70 levels increased with age irrespective of parity status, but were specifically reduced following OC tumor induction only in multiparous mice." (PMID 28966800, 2017). "Previous reports have shown that TNF signaling drives MDSC accumulation and favors tumor cell evasion." (PMID 28890718, 2017). "Several pro-inflammatory cytokines were found at higher concentrations in the spleen of both flank and orthotopic tumor-bearing groups when compared to sham, including KC (murine IL8 homologue), TNFα, and IL1β." (PMID 27901481, 2017). "HIFU-stimulated IFN-gamma and TNFα induction and increased CD86 expression in tumor tissue; this was mediated by miR-134 whose direct targets include CD86." (PMID 29112174, 2017). "Significant differences of IL-1β, IL-6, TNF-α and HGF were also detected in the comparison between tumor and non tumor HF and LF-HC bearing mice." (PMID 28881825, 2017). "MSCs treated with TNF-α and IFN-γ promote tumor growth in C57 syngeneic mouse model, correlating with increased serum level of PDGF, VEGF." (PMID 29268703, 2017). "The breadth of responses includes anti-tumor effector (Granzyme B, IFN-γ, MIP-1α, TNF-α), stimulatory (GM-CSF, IL-2, IL-8), regulatory (IL-4, IL-13, IL-22), and inflammatory (IL-6, IL-17A) functions." (PMID 29157295, 2017). "Increased expression of Th1 cytokines (IFN-γ and TNF-α) and attenuation of TGF-β expression in tumor microenvironments positively correlated with enhanced tumor-specific adaptive immune responses." (PMID 28002796, 2017). "A remarkable immunomodulatory effect was reflected by the augmentation of IL-2, 6, 12, Tumor necrosis factor-α (TNF-α), and interferon-gamma (IFN-γ) productions from the spleen lymphocytes of C. versicolor-treated tumor-bearing mice." (PMID 28885559, 2017). "Hiratsuka and colleagues showed that primary tumor cells release VEGF-A, TGFβ and TNFα that in turn, induces the expression of the chemoattractants such as S100A8 and S100A9 by lung endothelium and myeloid cells." (PMID 29340117, 2017). "Conversely, the combination of Abnormal Savda Munziq with 5-FU increased the levels of glutamine, TNF, IL, and BCAA in serum, demonstrating that the Abnormal Savda Munziq inhibited tumor growth by regulating immune function." (PMID 29190948, 2017). "TNF-α, a main pro-inflammatory cytokine in the TME, has been proposed to enhance tumor development and progression." (PMID 28170411, 2017).
tumor (continued). "Experiments with tumor-fibroblast co-cultures revealed that fibroblasts increase expression of TGF-β, TNF, and IL-1β cytokines in tumor cells, as well as stimulate TGF-β signaling." (PMID 28423685, 2017). "RdB/IL12/DCN-treated groups exhibited significantly higher IFN-γ and TNF-α than groups treated with PBS, RdB, RdB/IL12, or RdB/DCN (P < 0.001), suggesting that RdB/IL12/DCN induced a potent tumor-specific adaptive immune response." (PMID 28002796, 2017). "Among various bDMARDs, concern is greatest with anti-tumor necrosis factor (anti-TNF) therapies, given the established role of TNF in tumor progression and surveillance." (PMID 29246243, 2017). "IL-1β and KC/GRO were found in both xenografts and non-tumour bearing NOD-scid, whereas IL-6 and TNF-α were exclusively detected in xenograft tissue." (PMID 28417956, 2017). "MSCs profoundly reduced infiltration of macrophages, TNF-α-producing dendritic cells (DCs), TNF-α-, and IL-17-producing CD4+ T cells but increased IL-10-producing CD4+ T lymphocytes in the lungs of tumor-bearing animals." (PMID 28798777, 2017). "Anti-PD-L1 therapy in vivo led to tumor regression with increased antigen-reactive T cell infiltrate and increased IFN-γ and TNF-α production upon antigen stimulation ex vivo." (PMID 29255458, 2017). "The antitumor effects were likely due to decreased endothelial cell adhesion and survival in response to TNF-α and IFN-γ leading to destruction of tumor vasculature." (PMID 29276511, 2017). "Patient 5, the only patient evaluable 14 days after their third vaccination (D71), demonstrated a vaccine-induced increase in tumor-specific secretion of IFN-γ and TNF-α that was respectively 2-fold and 6-fold higher than baseline." (PMID 29258618, 2017). "PDL-1 expressions in tumor cells and hematopoietic cells are determined by the stimulation of pro-inflammatory cytokines such as IFN-γ and TNF-α." (PMID 28878676, 2017). "TNF-α promotes PDAC proliferation, induces the invasiveness of human PDAC cells and promotes tumor growth and metastasis in mice models." (PMID 28282928, 2017). "Recent studies have demonstrated that tumor-infiltrated CD8+ T cells display several functional impairments, especially in their polyfunctional cytokine production that includes IFN-γ, TNF-α, and CD107a, which are high-quality effectors." (PMID 28537894, 2017). "Pro-inflammatory cytokines including tumor necrosis factor-α, RNAKL and IL-6 were reported to induce VEGF-C induction in macrophages, astrocytes, fibroblasts, osteoclasts, as well as in tumor cells." (PMID 27383632, 2016). "In summary, anti-TNF-α treatment synergized with standard chemotherapy in PDAC mouse model to delay tumor growth and prolong mice survival via enhancing tumor apoptosis." (PMID 27835602, 2016). "Survivin can show chemotherapeutic resistance to cisplatin, bortezomib, vincristine, tamoxifen, TNF-a and TRAIL in tumor cells." (PMID 27330887, 2016). "We further observed that tumor-infiltrating CD3+CD56+ NKT-like cells had impaired effector function as shown by decreased IFN-γ, TNF-α, granzyme B and Ki-67 expression." (PMID 27409423, 2016). "Tumor necrosis factor-alpha (TNF-α), a vital pro-inflammatory cytokine in tumor microenvironment (TME), acts as an endogenous tumor promoter to facilitate invasion and metastasis." (PMID 27556690, 2016). "The transcription of the MMPs is induced by inflammatory cytokines, such as IL-1, IL-6, TNF-α, and growth factors such as EGF, HGF, and TGF-β, giving them a preponderant role in the chronic inflammation which is present in the tumour microenvironment." (PMID 26913068, 2016). "Next, tumor cells were irradiated and cultured in the presence of BV6 and a TNFα neutralization antibody." (PMID 27014915, 2016). "When LDLN cells from Salmonella-treated mice were exposed to tumor cells, the levels of IFN-γ and TNF increased, whereas the levels of IL-2 decreased with respect to the unexposed culture from the same group." (PMID 26973649, 2016).
tumor (continued). "The tumor stimulating activities of the eight analyzed growth factors, including VEGF, EGF, PDGF-BB, NGF-β, SCF, TNF-α, FGF-β, and TGF-β, have been demonstrated in many studies." (PMID 27151407, 2016). "The mRNA levels of colorectal inflammatory cytokines TNF-α, IL-1β, IL-6, CSF-1, and MCP-1, and COX-2 were increased in tumor and surrounding tissues from AOM/DSS-treated mice." (PMID 27557503, 2016). "Our data showed that BF-rTK + GCV system inhibited both TNF-α and its receptor, TNFR1, expression in tumor tissue, which indicated that BF-rTK + GCV inhibited inflammation induced by TNF-α/TNFR1 pathway." (PMID 27464624, 2016). "In vitro, the joint activity of the three factors, applied together as TME Stimulation (estrogen+TNFα+EGF), was much more potent than of each factor alone, leading to tumor cell remodeling towards an EMT-like phenotype and increased tumor cell scattering." (PMID 27835603, 2016). "We used the dose of 1 μg/mouse for TNFα and TCP-1/TNFα and 5 μg/mouse for IFNγ and TCP-1/IFNγ according to previous experiment which indicated that 5 μg TCP-1/IFNγ can induce maximal anti-tumor effect." (PMID 27342639, 2016). "Using a clonogenic assay, we found that stimulation of the NFκB pathway using TNF-α led to increased resistance of UM-HMC-3A and UM-HMC-3B tumor cells to IR." (PMID 27682876, 2016). "These ligands, namely TNF, Fas ligand (FasL), and TNF-related apoptosis-inducing ligand (TRAIL) activate their corresponding receptors present on the tumor cells, inducing apoptotic or necroptotic cell death." (PMID 27843441, 2016). "TNF-α released from macrophages was proposed to activate β-catenin through GSK-3β and Akt signaling in tumor cells, thereby promoting proliferation of the latter." (PMID 27713747, 2016). "Further inhibition of hypothalamic TNF signaling with ICV infliximab can partially restore the body weight, increase food intake and enhanced survival rate in both septic and tumor-bearing animals." (PMID 27922103, 2016). "Despite similar methods of activation and similar ratios of CD4 to CD8 T cells, we observed almost a ten-fold difference in TNF-α, IL-6 and IFN-γ released from F9 T cells compared to F38 T cells in response to tumor cells 24JKERB." (PMID 27153556, 2016). "The findings have shown that protein which includes the likes of Eotaxin, Fas ligand, IGF-II, IL-1β, TNF-α, IL-13, Leptin, and TIMP-1 were decreased when compared to the untreated tumor." (PMID 27558166, 2016). "Expression of TNF-α was higher in chemo-resistant PDAC cells than untreated PDAC cells, suggesting that TNF-α involves in chemoresistance of PDAC tumor cells and is a potential target for overcoming the chemoresistance." (PMID 27835602, 2016). "When transported by EVs, miR-21 can also induce tumor progression via pro-metastatic inflammatory responses by binding to Toll-like receptors and activation of NF-κB-IL6/TNF-alpha signaling." (PMID 27683108, 2016). "We then evaluated the effects of systemic TNF ablation on MDSC accumulation by treating mice with etanercept and compared MDSC levels in the blood of tumor-bearing and tumor-free mice." (PMID 27148266, 2016). "It is therefore likely that the expression of TNFα by mast cells of both the MCT and MCTC phenotypes within the tumour islets has important biological consequences." (PMID 27922077, 2016). "Tumour-infiltrating MDSCs treated with C-dextran and PEI secreted significantly higher levels of IL-12 and TNF-α, but produced lower levels of IL-10 and TGF-β than the control group." (PMID 27074905, 2016). "Most interestingly, combination treatment by TCP-1/TNFα and TCP-1/IFNγ dramatically inhibited tumor growth." (PMID 27342639, 2016). "On the other hand, late contact of MDM with TMVs, stimulated MDM to significant TNF and IL-12 secretion, ROI production and enhanced cytotoxicity against tumour cells in vitro." (PMID 26838097, 2016).
tumor (continued). "We investigated the mast cell phenotype in terms of protease content (tryptase-only [MCT], tryptase + chymase [MCTC]) and tumour necrosis factor-alpha (TNFα) expression, and extent of degranulation, in NSCLC tumour stroma and islets." (PMID 27922077, 2016). "In summary, we demonstrated that competitive displacement of SMAC from the BIR3 domains of cIAP1 and cIAP2 correlates closely with sensitization of tumor cells to TNFR1 agonists, TNF and LT-α." (PMID 27617834, 2016). "Under normoxia, MMP1 and integrin (ITGA4) were elevated in TNF-α and TNFα/IL-1β clones; these can degrade the ECM component and play a role in the development of tumour metastasis." (PMID 26759080, 2016). "These cells perform their immune stimulatory function by secretion of pro-inflammatory cytokines, such as tumor necrosis factor (TNF)-α, interleukin-1 (IL-1), IL-6, and IL-12 combined with a strong capacity to process and present tumor antigens." (PMID 27065074, 2016). "Upon incubating B7-H3Bi-armed ATC with the tumor cells, we detected high levels of IFN-γ and TNF-α secreted by B7-H3Bi-armed ATC." (PMID 27121051, 2016). "These tumor-specific CTL had characteristics similar to antiviral CTL, including strong expression of activation markers and co-expression of IFNγ and TNFα." (PMID 26961085, 2016). "TNFα activates NFκB and MAPK signaling and promotes inflammatory responses, particularly against tumor cells." (PMID 27164082, 2016). "Within the tumor microenvironment, increasing numbers of B and T cells infiltrating into tumors and large percentages of INF-γ- and tumor necrosis factor (TNF) -α-producing tumor-infiltrating T cells in the transferred mice are observed." (PMID 27331871, 2016). "TCP-1/TNFα combined with TCP-1/IFNγ induced massive cell death in the tumor (>90 %) as shown by the TUNEL staining and also cell death of the tumor vasculature." (PMID 27342639, 2016). "There was a relationship between the concentration of both TNF-α and VEGF and the histological grade of the tumour (G) and the size of tumour (T stage), while TGF-β level was related to N stage." (PMID 27547238, 2016). "Compared with the unconjugated TNFα and IFNγ, the conjugated groups through TCP-1 further increased the infiltration of both CD8+ and CD4+ T cell in the tumor." (PMID 27342639, 2016). "Conversely, TIS-CD8+ T cells promote CD16+ expression in monocytes/macrophages and the production of pro-inflammatory cytokines (TNF, IL-1β, and IL-6) and angiogenic factors (MMP-9, VEGF-A, and IL-8), which can affect tumor progression." (PMID 27129159, 2016). "Inflammatory cytokines, such as tumor necrosis factor (TNF)-α, interleukin (IL)-1β and IL-6, produced by a tumor and/or activated by immune cells, have been shown to stimulate cancer cell growth and influence clinical disease status and prognosis." (PMID 26959121, 2016). "We subsequently measured the mRNA levels of PD-L1, CD80, CD8, TNF-α and IFN-γ via RT-PCR in ID8 tumours." (PMID 27147225, 2016). "Tumors require a blood supply to survive and the tumor microenvironment includes a high level of cytokine activity (including COX-2, TNF-α and interleukins)." (PMID 27120781, 2016). "The IPA analysis also revealed a significant increase in TNF signaling, which is consistent with the recent study that suggested NLRX1 functions as a tumor suppressor through modulating this pathway in cancer cells." (PMID 27105514, 2016). "Further, we demonstrated in accordance with the previous reports that when M14 tumor cells were cultured in the condition of IFN-γ and TNF-α, PD-L1 expression were up-regulated." (PMID 26818188, 2016). "cFLIP inhibition or down-regulation has therefore been proposed as a potential cancer therapy with the assumption that this will operate by sensitizing tumor cells to Fas-, TRAIL-, or TNF-induced cell death (for a review, see Ref." (PMID 26865630, 2016).
tumor (continued). "On the other hand, tumor cells can produce some of the same cytokines, angiogenic, and growth factors released by MSC such as IL-8, PDGF, EGF, TGF-β, IL-1β, and TNF-α, which can trigger MSC migration." (PMID 27834810, 2016). "The IFN-γ, TNF-α, NO levels in splenocytes supernatant, as well as iNOS, IFN-γ, Granzyme B mRNA levels in splenocytes and tumor blocks were significantly increased." (PMID 27246354, 2016). "Some of their substrates are growth factors or cytokines such as TNF-α and EGF, relevant for development and tumor cell expansion." (PMID 27834810, 2016). "Macrophage cytotoxicity in tumors can be mediated by cytokines such as tumor necrosis factor (TNF), by direct phagocytosis or combination of both, although primary elimination of tumor cells by macrophages occurs via phagocytosis." (PMID 27671753, 2016). "The genetic and epigenetic alterations acquired by carcinoma cells during primary tumor formation are likely to increase their responsiveness to various contextual signals such as TGF-β, TNF-α, IL-6 and EGF." (PMID 26909601, 2016). "M1 macrophages produce large amounts of pro-inflammatory cytokines such as TNF-α, COX-2 and IL-6, which can generate NO and ROS and express high levels of MHC molecules functioning as killers of pathogens and tumour cells." (PMID 27907187, 2016). "Quantitative RT-PCR was used to determine the expression of TNF, COX2, MMP9 and CTNNB (catenin beta) in tumor samples." (PMID 27323816, 2016). "In summary, ASMq demonstrates anti-tumor effects and downregulates the expression of TGF-β1 and upregulates the expression of TNF-α in vivo." (PMID 27881109, 2016). "To dissect the relative roles of apoptosis and necroptosis in tumor cell death, we treated tumor cells with BV6 and TNFα in the presence of apoptosis and necroptosis inhibitors." (PMID 27014915, 2016). "Our results showed that despite the specificity of action, the inhibitors significantly reduced invasion and migration enhanced by TNFα and PMA in human GBM cell line and primary cultures derived from GBM tumor." (PMID 26940200, 2016). "Consistent with flow cytometry data, the numbers of IFN-γ- and TNF-α-producing CD4 and CD8 T cells in spleen and tumor drLN were significantly increased by ascophyllan treatment." (PMID 27008707, 2016). "In a parallel experiment, sera of mice bearing either 4T1 tumours or CT26 tumours after different treatments were collected at 24, 72 and 168 h to analyse the changes of various cytokines including IL-6, TNF-α and IL-12p70." (PMID 27767031, 2016). "The anti-tumor effect is also achieved by secretion of Interferon gamma (IFN-ɣ) and TNF alpha (TNF-α) from activated CD8+ T cells." (PMID 27686848, 2016). "The proportion of CD4+ cells that secrete TNF-α and IFN-γ upon stimulation decreased after radiation in both tumours suggesting a decreased TH-1 response." (PMID 28008921, 2016). "Although there are no significant changes in the expression of pro-inflammatory cytokines, such as TNF-α, TGF-β, INF-γ and IL-6, we found a significant overexpression of the anti-inflammatory cytokine IL-10 within the tumor mass of B1−/− mice." (PMID 26898917, 2016). "To further clarify how the cells in the tumor died after TCP-1/TNFα and TCP-1/IFNγ combined treatment, we used the colon 26 cells to determine the effect of TNFα combined with IFNγ in vitro." (PMID 27342639, 2016). "Among the tumor necrosis factor (TNF) ligands, TNF-related apoptosis-inducing ligand (TRAIL) is unique due to its capacity to selectively induce cell death in tumor cells." (PMID 27166192, 2016). "When encountering tumor antigens, these TILs can directly kill tumor cells and release cytokines, such as IFN-γ, IL-2, and TNF, which are known to mediate antitumor immune responses." (PMID 27683579, 2016). "This is due to the secretion of the epidermal growth factor (EGF), platelet-derived growth factor (PDGF), TGF-β, IL-6, IL-1, and tumor necrosis factor (TNF)-α of TAMs, which creates a favorable milieu for tumor growth." (PMID 27044404, 2016).